PKLR (pyruvate kinase L/R)
Description:
Pyruvate kinase that catalyzes the conversion of phosphoenolpyruvate to pyruvate with the synthesis of ATP, and which plays a key role in glycolysis. Also produces the side product 2-phospholactate which can inhibit fructose-2,6-bisphosphate production. 2-phospholactate can be dephosphorylated by PGP which prevents the inhibition of fructose-2,6-bisphosphate production and allows glycolysis to occur.
Synonyms: PK1; PKL; CNSHA2; PKRL; RPK
Tractability: Small molecule: an approved drug acts on it; a structure with a bound ligand is known; a high-quality ligand is known; it has a high-quality binding pocket; it belongs to a druggable protein family. PROTAC: ubiquitination databases record sites on it; a small molecule that binds it is known.
Target class: Enzyme
Gene: Protein-coding gene on chromosome 1 (155,289,293 to 155,301,438, reverse strand). Ensembl gene ENSG00000143627.
Subcellular location (Human Protein Atlas): Cytosol
Pathways (Reactome):
Metabolism: ChREBP activates metabolic gene expression; Glycolysis; Pyruvate metabolism
Developmental Biology: Regulation of gene expression in beta cells
Disease: SARS-CoV-1-host interactions
Gene Ontology:
Molecular function: protein binding; pyruvate kinase activity; magnesium ion binding; monosaccharide binding; potassium ion binding
Biological process: canonical glycolysis; cellular response to insulin stimulus; glycolytic process; pyruvate biosynthetic process; cellular response to epinephrine stimulus; response to ATP; response to cAMP; response to glucose; response to hypoxia; response to metal ion; response to nutrient
Cellular component: extracellular exosome; cytosol
Genetic constraint (gnomAD): Loss-of-function variants: 38 observed, 55.26 expected, observed/expected ratio (o/e) 0.69, 90% interval 0.53 to 0.9. The upper end of that interval is the gene's LOEUF score, 0.9, which puts it in group 3 of 6, group 1 being the genes least tolerant of losing a copy. Missense variants: 691 observed, 816.65 expected, observed/expected ratio (o/e) 0.85, 90% interval 0.79 to 0.9. Synonymous variants: 322 observed, 331.85 expected, observed/expected ratio (o/e) 0.97, 90% interval 0.88 to 1.06.
Gene-disease validity (ClinGen):
ClinGen rates the evidence that PKLR causes each of these diseases.
pyruvate kinase deficiency of red cells (autosomal recessive): Definitive.
Homologues: Orthologues: chimpanzee PKLR (99% identical), rabbit PKLR (94% identical), macaque PKLR (93% identical), dog PKLR (93% identical), rat Pklr (91% identical), pig PKLR (89% identical), guinea pig PKLR (89% identical), mouse Pklr (88% identical), tropical clawed frog pklr (71% identical), zebrafish pklr (64% identical), Caenorhabditis elegans pyk-1 (55% identical), Drosophila melanogaster PyK (53% identical), and 4 more. Paralogues in human: PKM (66% identical).
Diseases named in the same sentence as PKLR in open-access papers:
PKLR is named in the same sentence as 68 diseases in open-access papers, as found by Europe PMC text mining. Sharing a sentence is not in itself a finding about the gene and the disease. The quoted sentences say what the papers report.
pyruvate kinase deficiency (19 papers, 2015 to 2025). "Pyruvate kinase deficiency (PKD) is a rare autosomal recessive disorder characterized by mutations in the PKLR gene, causing impaired glycolysis in red blood cells and leading to diverse clinical manifestations." (PMID 38736761, 2024). "Pyruvate kinase deficiency (PKD) is an autosomal recessive genetic disease caused by mutations in the PKLR gene." (PMID 39635530, 2024). "Pyruvate kinase deficiency (PKD) is an autosomal recessive disorder caused by mutations in the PKLR gene." (PMID 37188156, 2023). "After all, pyruvate kinase deficiency is the most common enzymatic disorder detected in newborns, and a wide variety of disease-causing PKLR variants have been identified." (PMID 37792629, 2023). "Hemolytic anemia has been approached by transduction of HSCs by LV expressing the pyruvate kinase L/R (PKL/R) to compensate for pyruvate kinase deficiency (PKD), which corrected the hematological phenotype in mice." (PMID 36992407, 2023). "Pyruvate kinase deficiency is an exceptionally rare autosomal recessive Mendelian disorder caused by bi-allelic pathogenic variants in the PKLR gene." (PMID 35168679, 2022). "We present here a novel genetic defect in the PKLR gene that correlates with pyruvate kinase deficiency phenotype in a consanguineous family from North-Western Pakistan." (PMID 35168679, 2022). "In summary, these findings suggest a novel genetic defect in the PKLR gene as a likely cause of pyruvate kinase deficiency, thus further expanding the mutational landscape of this rare Mendelian disorder." (PMID 35168679, 2022). "She had repeated admissions due to similar illnesses and at the age of 8 years was found to have pyruvate kinase deficiency associated with a novel homozygous pathogenic variant c.507+1delG in the PKLR gene." (PMID 34311792, 2021). "Pyruvate kinase deficiency (PKD) disease: Mutations in the pyruvate kinase Isozymes R/L (PKLR) gene cause premature destruction of red blood cells resulting in PKD disease." (PMID 34503562, 2021). "This case report identifies a new pathogenic variant in PKLR gene detected in a patient with severe pyruvate kinase deficiency." (PMID 34311792, 2021). "Pyruvate kinase deficiency (PKD) is a rare congenital hemolytic anemia caused by mutations in the PKLR gene." (PMID 33551834, 2020). "Pyruvate Kinase Deficiency (PKD) is a rare erythroid metabolic disease caused by mutations in the PKLR gene, which encodes the erythroid specific Pyruvate Kinase enzyme." (PMID 31618280, 2019). "Pyruvate kinase deficiency (PKD) is a rare erythroid metabolic disease caused by mutations in the PKLR gene." (PMID 26549847, 2015). "However, a survey of erythrocyte pyruvate kinase deficiency (OMIA 000844-9685) revealed mutant allele frequencies of the PKLR:c.707-53G>A mutation to be 0.214 in Abyssinian cats, 0.229 in Somali cats, 0.016 in Bengal cats, and 0.008 in American Shorthair cats." (PMID 40869986, 2025). "Pyruvate kinase deficiency (PKD) is a rare, autosomal recessive disorder characterized by mutations in the PKLR gene, leading to impaired glycolysis in red blood cells." (PMID 38736761, 2024). "Pyruvate kinase deficiency (PKD; OMIM: 266200) is a rare metabolic erythroid disease caused by mutations in the PKLR gene, which codes the R-type pyruvate kinase (RPK) in erythrocytes and L-type pyruvate kinase (LPK) in hepatocytes." (PMID 26549847, 2015). "Homozygous or compound heterozygous variants of the PKLR gene cause pyruvate kinase deficiency or congenital non-spherocytic hemolytic anemia-2, which is the most common hereditary glycolytic enzyme disorder." (PMID 40130200, 2025). "Pyruvate Kinase Deficiency (PKD) is a rare autosomal recessive non-spherocytic hemolytic anemia produced by mutations in the PKLR gene." (PMID 37188156, 2023). "rs116100695 is a rare missense variant in PKLR causing red cell pyruvate kinase deficiency, a common cause of hereditary nonspherocytic hemolytic anemia." (PMID 27863252, 2016).
pyruvate kinase deficiency (continued). "In the case of lentivirus-based gene therapy, a lentiviral vector carrying the human pyruvate kinase deficiency (hPKD) promoter and the PKLR gene was employed for addressing the monogenic metabolic disease PKD caused by mutations in the pyruvate kinase isoenzymes L/R (PKLR) gene." (PMID 29883422, 2018).
gallbladder cancer (9 papers, 2019 to 2024). "USP3 promotes gallbladder cancer proliferation by modifying the deubiquitination level of pyruvate kinase L/R, and USP3 facilitates breast cancer progression through KLF5 deubiquitination." (PMID 38531846, 2024). "CircFOXP1 can interact with PTBP1, inhibit the 3′ UTR and CDS regions of PTBP1-binding PKLR mRNA, promote the expression of PKLR, and accelerate the appearance and development of gallbladder cancer." (PMID 39199340, 2024). "In our previous study, we described and demonstrated that circFOXP1 (hsa_circ_0008234) expression was significantly increased in gallbladder cancer and enhanced tumor progression and the Warburg effect in gallbladder cancer via regulating PKLR expression." (PMID 38745044, 2024). "For example, FOXP1 drives the occurrence of malignant behaviour by dominating the expression level of PKLR in gallbladder cancer." (PMID 36160018, 2022). "In gallbladder cancer, our previous study showed that circular RNA FOXP1 promotes tumor progression and Warburg effect in gallbladder cancer by regulating PKLR expression." (PMID 34489401, 2021). "Compared with normal tissues, PTBP1 was upregulated in gallbladder cancer tissues and the protein and mRNA of PKLR was also upregulated in gallbladder cancer tissues." (PMID 31623628, 2019). "In our previous study, we identified that circFOXP1 expression was remarkably upregulated in gallbladder cancer tissues and cells, and promoted tumor progression and the Warburg effect in GBC cells by regulating PKLR expression." (PMID 38745044, 2024). "CircFOXP1 interacts with PTBP1, which binds to the 3′-UTR region and coding region of PKLR mRNA (UCUU sequences) to impair the decay of PKLR mRNA, thereby promoting Warburg effect in gallbladder cancer progression." (PMID 34168116, 2021). "In gallbladder cancer, circFOXP1 stimulated the cell Warburg effect by interacting with the RBP polypyrimidine Tract-binding protein 1 (PTBP1), which significantly increased the expression of pyruvate kinase PKLR and protected PKLR mRNA from degradation." (PMID 33710802, 2021).
hepatocellular carcinoma (6 papers, 2015 to 2023). A malignant tumor that arises from hepatocytes. "Nontargeted and targeted metabolomic assays were performed in human hepatoma cells transfected with lentiviral vectors causing PKLR overexpression and silencing, respectively." (PMID 34512869, 2021). "The effects of altered PKLR expression on the metabolomic profiles of hepatoma cells and grafts suggest the need to assess its function in specific scenarios." (PMID 34512869, 2021). "PC and lyso-PC played central roles as key mediators in pathways affected by PKLR in both hepatoma cells and LT grafts." (PMID 34512869, 2021). "We aimed to clarify the genetic impact of PKLR on the metabolomic profiles of hepatoma cells and its potential effects on grafts for liver transplantation (LT)." (PMID 34512869, 2021). "This systems-level analysis indicated that PKLR affected hepatoma cell viability via impacts on the whole process of DNL, from glycolysis to final PC synthesis." (PMID 34512869, 2021). "We also identified PKLR as a potential liver-specific target for treating hepatocellular carcinoma and nonalcoholic fatty liver disease." (PMID 34512869, 2021). "We assessed the molecular function of PKLR on global metabolites by integrating untargeted and targeted metabolomic and transcriptomic data in human hepatoma cells over- or underexpressing PKLR." (PMID 34512869, 2021). "The TCA cycle and pyruvate metabolism pathways were identified as the most likely pathways affected by PKLR expression in hepatoma cells." (PMID 34512869, 2021). "In addition to HK2 and LDHA, some researchers discovered that NR3C2 inhibits cellular aerobic glycolysis by regulating PKLR, an isozyme of pyruvate kinase, in hepatocellular carcinoma cells." (PMID 36950803, 2023). "miR-338-3p suppressed the Warburg effects of hepatocellular carcinoma (HCC) cells by targeting PKLR, indicating that miR-130a likely plays a role in HCC development." (PMID 29321333, 2018).
steatosis (6 papers, 2014 to 2024). Increased lipid within the cytoplasm of cells. "PKLR was proven to have a wide association with a spectrum of liver damage from steatosis and inflammation to fibrosis via its regulation on mitochondrial dysfunction and subsequent hepatic triglyceride accumulation, based on multiomic data at systematic levels." (PMID 34512869, 2021). "Additionally, a comparison between drugs causing phospholipidosis and/or steatosis revealed 26 genes to be regulated in common including 4 signature genes to predict DIS (PKLR, GK, FABP7 and FADS1)." (PMID 25470483, 2014). "And high-glucose levels resulted in severer steatosis and higher cellular TG and TC levels in cells overexpressing PKLR (P < 0.05)." (PMID 34512869, 2021). "Furthermore, a comparison between drugs inducing phospholipidosis and/or steatosis uncovered 26 commonly regulated genes, including from the signature markers (PKLR, GK, FABP7 and FADS1)." (PMID 38791241, 2024). "Furthermore, PKLR induced mitochondrial stress in both steatosis and fibrosis models, and silencing PKLR relieved this stress and promoted the resolution of NAFLD/NASH." (PMID 34869329, 2021). "In vivo knockdown experiments of PKLR improved both steatosis and insulin resistance." (PMID 34869329, 2021). "In addition, it has been shown that inhibition of PKLR in the liver leads to a decrease in OXPHOS in steatosis, suppressing mitochondrial respiration and reducing active production of ROS, which alleviates fatty liver." (PMID 34568346, 2021). "On the other hand, our results for PKLR and PDK4 appear to indicate a beneficial effect of TUG-891 on hepatic glucose metabolism in the context of the development of steatosis, as PKLR and PDK4 were shown to aggravate NAFLD." (PMID 36705799, 2024).
Hepatic steatosis (5 papers, 2014 to 2024). Steatosis is a term used to denote lipid accumulation within hepatocytes. "Furthermore, GK and PKLR that play a key role in glucose metabolism were repressed in expression and their altered expression is associated with hepatic steatosis." (PMID 25470483, 2014). "AAV6-mediated in vivo expression of the shRNA against pyruvate kinase L/R (PKLR) was reported to lower L-type pyruvate kinase expression in the liver of mice fed a high-fat and sucrose (HF/HS) diet, leading to alleviated IR and reduced liver steatosis." (PMID 38665220, 2024).
malaria (5 papers, 2012 to 2022). Malaria is a serious and sometimes fatal disease caused by a parasite that commonly infects a certain type of mosquito which feeds on humans. "The main aim of the present study was to examine the haematological profiles in malaria patients with G6PD or PKLR mutations." (PMID 36038921, 2022). "Our study showed an association of putative malaria-resistance variants in the PKLR gene with susceptibility to leprosy and TB in Brazilian populations with higher African content (Rio de Janeiro and Salvador) and in Africa (Mozambique)." (PMID 34449765, 2021). "Due to its involvement with ATP production and erythrocyte integrity, the PKLR gene is a putative target of selection being associated with adaptation to high-altitude in Tibetans and with malaria in Sub-Saharan Africa." (PMID 34449765, 2021). "We showed previously that in mice and humans, PKLR-deficiency is associated with increased resistance to malaria." (PMID 28542307, 2017). "We investigated the effect of PKLR genotypes on rich longitudinal datasets including haematological and malaria-associated phenotypes." (PMID 26658699, 2015). "We have characterized the genetic diversity of the PKLR gene, including haplotype structure and presence of rare coding variants in two populations from malaria endemic areas of Thailand and Senegal." (PMID 26658699, 2015). "Pyruvate kinase (PK) deficiency, caused by mutations in the pyruvate kinase, liver and RBC (PKLR) gene (chromosome 1q21) is one of the most recently described erythrocyte abnormalities associated to malaria." (PMID 23082140, 2012). "The current study examined an example of an evolutionary trade-off in which genetic variants in the PKLR gene putatively selected for malaria resistance influence the susceptibility to mycobacterial diseases (leprosy and tuberculosis) in Brazilian population and Mozambique." (PMID 34449765, 2021). "Pyruvate kinase (PKLR) deficiency protects mice and humans against blood-stage malaria." (PMID 28542307, 2017). "Herein, we probed for the possible association between rare or common variants at the sequenced PKLR gene, and haematological and malaria-associated phenotypes in three populations from Thailand and Senegal, living in areas of seasonal or year-long exposure to the malarial parasite." (PMID 26658699, 2015). "Using comparative analyses of archival populations contained in the CEPH Human Diversity panel from current and ancestral areas of malaria, we detected rich genetic diversity in the PKLR gene, including the presence of rare, potential loss-of-function protein variants." (PMID 26658699, 2015). "Moreover, some of the genes that confer resistance to malaria are among the most variable genes in the human genome and this is the case for PKLR gene, which presents more than 180 mutations and 8 polymorphic sites." (PMID 23082140, 2012). "In this study, we took advantage of two longitudinal population studies conducted in the malaria endemic areas of Senegal and Thailand, to identify whether PKLR gene variants are associated with protection against the incidence or severity of malarial infections." (PMID 26658699, 2015). "In human population, genetic screens have also suggested that mutations for PK deficiency have been selected due to their protective effect against the Plasmodium infection in malaria-endemic areas and there have been claims that the PKLR locus is under selective pressure in African populations." (PMID 34449765, 2021). "However, disease-based cohorts with single clinical end-points (presence or absence of disease) are not optimal to test the potential protective effects of PKLR variants on human malaria." (PMID 26658699, 2015). "Finally, re-sequencing the PKLR gene in human populations (21 ethnic groups, 6 geographical clusters) from current or ancestral areas of malaria endemicity (Africa, South-East Asia) identified a rich genetic diversity at human PKLR, and have suggested that the gene may be under selection." (PMID 28542307, 2017).
malaria (continued). "In addition, a strong linkage disequilibrium (LD) between PKLR and adjacent loci within individuals with no malaria infection or non-complicated malaria suggested a conserved genomic region probably selected due to some level of malaria protection." (PMID 34449765, 2021).
breast carcinoma (4 papers, 2022 to 2025). "Our previous work demonstrated that NQO1 can bind to pyruvate kinase L/R (PKLR), a key regulator of glycolytic reprogramming in breast cancer, thereby activating the AMPK and AKT/mTOR signaling pathways and inducing glycolytic reprogramming." (PMID 39939940, 2025). "HPR, PKLR and PLAU have been reported to be overexpressed in breast cancers and esophageal squamous cell carcinoma." (PMID 35327967, 2022).
maturity onset diabetes (4 papers, 2008 to 2025). "The pyruvate Kinase (PKLR) gene shows significant associations with Type 2 Diabetes." (PMID 32590936, 2020). "Moreover, a binding site for hepatocyte nuclear factor 1-α is located in the PKLR promoter and patients with maturity-onset diabetes of the young type 1 and 3 show decreased expression of the gene." (PMID 19111066, 2008). "The C-allele of PKLR rs3020781 and the T-allele of NOS1AP rs7538490 are reported to strongly associate with type 2 diabetes in various European-descent populations comprising a total of 2,198 individuals with a combined odds ratio (OR) of 1.33 [1.16–1.54] and 1.53 [1.28–1.81], respectively." (PMID 19111066, 2008). "We failed to provide evidence of an association between PKLR rs3020781 and NOS1AP rs7538490 and type 2 diabetes, overweight, obesity or related quantitative metabolic phenotypes in large-scale studies of Danes." (PMID 19111066, 2008).